MIR22HG (MIR22 host gene)
Synonyms: C17orf91; MGC14376; DKFZp686O06159
Gene: Long non-coding RNA gene on chromosome 17 (1,711,447 to 1,717,174, reverse strand). Ensembl gene ENSG00000186594.
Gene Ontology:
Cellular component: RISC complex
Diseases named in the same sentence as MIR22HG in open-access papers:
MIR22HG is named in the same sentence as 38 diseases in open-access papers, as found by Europe PMC text mining. Sharing a sentence is not in itself a finding about the gene and the disease. The quoted sentences say what the papers report.
lung carcinoma (12 papers, 2016 to 2024). "Abnormal expression of MIR22HG was associated with many tumors, including lung cancer, breast cancer, and thyroid cancer." (PMID 35342423, 2022). "In fact, in several lung cancer cell lines, MIR22HG downregulation causes a decrease in cMYC protein level." (PMID 31729379, 2019). "MIR22HG is downregulated and associated with patient survival in lung cancer." (PMID 32760219, 2020). "MIR22HG was also down-regulated in lung cancer and interacts with YBX1, MET and p21 to suppress cancer development." (PMID 32500915, 2020). "We found that MIR22HG is the mostly investigated one in cancer and has been show to function as a tumor suppressor in hepatocellular carcinoma, lung cancer and thyroid cancer." (PMID 32127004, 2020). "Existing studies have shown that MIR22HG functions as a tumor suppressor in many cancers, such as gastric cancer, colorectal cancer, esophageal cancer, lung cancer and hepatocellular carcinoma." (PMID 33267888, 2020). "MIR22HG, which is downregulated in lung carcinoma, was found to be upregulated in ACBP monotherapy cells and ACBP and ASLB combination-treatment cells." (PMID 29156779, 2017). "Clinically, the expression of MIR22HG is increased in many human tumors (colorectal cancer, gastric cancer, hepatocellular carcinoma, lung cancer, and thyroid carcinoma), while in others (esophageal adenocarcinoma and glioblastoma), it is significantly decreased." (PMID 33267888, 2020). "Silencing of MIR22HG can also triggers cell survival/death signaling via oncogenes YBX1, MET, and p21 in lung cancer." (PMID 32127004, 2020). "MIR22HG (MIR22 host gene) is a tumor suppressor lncRNA involved in proliferation and progression of several types of cancer such as lung cancer." (PMID 32760219, 2020).
hepatocellular carcinoma (9 papers, 2018 to 2024). A malignant tumor that arises from hepatocytes. "Our previous microarray analysis showed that the expression level of MIR22HG was moderately up-regulated after hepatoma cells were irradiated compared to that of a control group." (PMID 33718133, 2021). "MIR22HG can also competitively bind to human antigen R (HuR), resulting in weakened expression of HuR-stabilized oncogenes, such as β-catenin in hepatocellular carcinoma cells." (PMID 32127004, 2020). "More recently, MIR22HG has also emerged as exhibiting ceRNA functions in many cancer types, such as thyroid carcinoma (TC), endometrial carcinoma (EC) and hepatocellular carcinoma (HCC)." (PMID 33267888, 2020). "MIR22HG is transcribed from the gene locus harboring miR-22 and inhibits cell invasion in hepatocellular carcinoma by deriving miR-22 (Liu, Zhang & Wu, 2016)." (PMID 30038865, 2018). "For instance, MIR22HG was down-regulated in hepatocellular carcinoma and its overexpression may affect miR-10a-5p/NCOR2 axis to suppress the invasion, migration and proliferation of cancer cells." (PMID 32500915, 2020). "Studies have shown that a high expression of MIR22HG is positively correlated with the OS of patients with hepatocellular carcinoma following hepatectomy, and a high expression of MIR22HG could suppress gastric cancer progression by attenuating NOTCH2 signalling." (PMID 32964046, 2020).
glioblastoma (7 papers, 2020 to 2023). The most malignant astrocytic tumor (WHO grade IV). "Han and coworkers demonstrated that MIR22HG was significantly upregulated in glioblastoma and it promoted the malignant phenotypes of glioblastoma through Wnt/β-catenin signaling pathway." (PMID 34187303, 2021). "Conversely, some studies showed that MIR22HG played an oncogenic function in several cancer types such as glioblastoma, and MIR22HG knockdown inhibits the invasion and proliferation of cancer cells." (PMID 32732881, 2020). "For instance, MIR22HG is an oncogenic lncRNA which has been shown to be highly dysregulated in glioblastoma via assessment of accessible datasets." (PMID 33634032, 2020). "Notably, the long non-coding RNA MIR22HG which was reported to facilitate the progression of glioblastoma via regulation of Wnt/β-catenin signaling coincides with our findings." (PMID 37934582, 2023). "However, in esophageal adenocarcinoma and glioblastoma, MIR22HG acts as a tumor promoter to facilitate tumor progression." (PMID 33267888, 2020). "Over-expression of MIR22HG in glioblastoma samples has been related with poor patients’ outcome." (PMID 33634032, 2020). "For instance, lncRNA MIR22HG regulates GBM progression through Wnt/β-catenin signaling, whereas HOTAIRM1 promotes tumor aggressiveness and radiotherapy resistance in glioblastoma." (PMID 35191808, 2022).
glioma (7 papers, 2020 to 2023). A benign or malignant brain and spinal cord tumor that arises from glial cells (astrocytes, oligodendrocytes, ependymal cells). "Despite the fact that many lncRNAs (e.g., TUG1 and MIR22HG) have been revealed to be markedly dysregulated in gliomas, the functions and mechanisms of lncRNAs in gliomas have not yet been explored thoroughly." (PMID 37100464, 2023). "The dysregulated ceRNAs also contained 17 long noncoding RNAs (lncRNAs), such as MALAT1 and MIR22HG, which had been proved to play important roles in glioma." (PMID 35496054, 2022). "For instance, lncRNA MIR22HG is a critical inducer of the Wnt/β-catenin signaling pathway, which provides a potential therapeutic strategy for glioma patients by targeting the lncRNA MIR22HG." (PMID 34099027, 2021). "A nine-EMT-related lncRNAs (HAR1A, LINC00641, LINC00900, MIR210HG, MIR22HG, PVT1, SLC25A21-AS1, SNAI3-AS1, and SNHG18) signature was identified in patients with glioma." (PMID 34288803, 2021). "Among the nine EMT-related lncRNAs identified in this study, LINC00900, MIR210HG, MIR22HG, PVT1, and SNHG18 were positively correlated with glioma malignancy, whereas HAR1A, LINC00641, SLC25A21-AS1, and SNAI3-AS1 were negatively correlated with glioma malignancy." (PMID 34288803, 2021).
colorectal cancer (6 papers, 2020 to 2024). A primary or metastatic malignant neoplasm that affects the colon or rectum. "MIR22HG is demonstrated as a tumor suppressor through TGF-β/SMAD signaling in colorectal cancer, whose depletion can promote EMT process and tumor metastasis." (PMID 36467998, 2022). "Moreover, we found that MIR22HG exerts its biological function by inhibiting the growth and migration of colorectal cancer cells through SMAD2 and TGFβ signaling pathway." (PMID 32127004, 2020). "Besides, it has been shown that various lncRNAs such as MIR22HG and LINC01600 play an important role in colorectal cancer." (PMID 33194594, 2020).
gastric cancer (6 papers, 2019 to 2024). A primary or metastatic malignant neoplasm involving the stomach. "MIR22HG suppressed gastric cancer progression through attenuating NOTCH2 signaling MIR22HG repressed cell proliferation, migration and invasion in CCA by negatively regulating the Wnt/β-catenin signaling pathway." (PMID 31291201, 2019). "Recently, some reports show that one lncRNA MIR22HG suppresses the cell progression in several cancer, such as cholangiocarcinoma, hepatocellular carcinoma, gastric cancer, and lung cancer." (PMID 31291201, 2019). "Meanwhile, E2F6 suppresses Dnmt3b recruitment to mediate germ-line gene silencing in murine somatic tissues, and downregulates MIR22HG and lncRNA CASC2 participating in laryngocarcinoma and gastric cancer progression, respectively." (PMID 39767802, 2024). "MIR17HG and MIR22HG have been wildly investigated in many cancers, including CRC, gastric cancer, and MIR17HG was also related to the paclitaxel resistance in ovarian cancer." (PMID 37245016, 2023).
breast carcinoma (5 papers, 2016 to 2022). "Notably, our results showed that loss-of-function of MIR22HG enhanced the proliferation and migration abilities of breast cancer cells." (PMID 34446703, 2021). "In summary, we have identified five novel lncRNAs (AL117190.1, COL4A2‐AS1, LINC00184, MEG3 and MIR22HG) related to prognosis of breast cancer, which could act as underlying prognosis biomarkers for breast cancer." (PMID 31613058, 2019). "Taken together, our results suggest that MIR22HG acts as a miR-629-5p sponge that can inhibit the proliferation and migration of breast cancer cells and stabilize LATS2 expression." (PMID 34446703, 2021). "To identify the downstream targets of MIR22HG and miR-629-5p, we analyzed the breast cancer data from The Cancer Genome Atlas (TCGA) database and found that LATS2 expression was positively correlated with MIR22HG expression." (PMID 34446703, 2021). "Collectively, our results suggest that gain-of-function of MIR22HG inhibited the proliferation of breast cancer cells both in vitro and in vivo." (PMID 34446703, 2021). "Results showed that MIR22HG overexpression suppressed the proliferation and migration of breast cancer cells." (PMID 34446703, 2021). "In this study, we aimed to determine the function and molecular mechanism of MIR22HG in breast cancer progression using transcriptomics and biotechnological techniques." (PMID 34446703, 2021). "To determine the function of MIR22HG in breast cancer, we investigated 36 pairs of cancerous tissues and adjacent normal breast tissues via real-time PCR." (PMID 34446703, 2021). "Functional analysis via siRNA-induced knockdown of MIR22HG resulted in the enhanced proliferation and metastasis of breast cancer cells, while MIR22HG overexpression inhibited cancer cell proliferation and metastasis." (PMID 34446703, 2021). "Collectively, our results suggest that MIR22HG act as a miRNA sponge that can inhibit function of miR-629-5p in breast cancer cells." (PMID 34446703, 2021). "Through survival analysis, 5 lncRNAs (AL117190.1, COL4A2‐AS1, LINC00184, MEG3 and MIR22HG) were identified as crucial prognostic factors for patients with breast cancer." (PMID 31613058, 2019). "Adenosine and adenine repress the long non-coding RNA MIR22HG expression, therefore upregulating cMYC protein level and inducing downstream metabolic changes and breast cancer cell growth." (PMID 31729379, 2019). "From this analysis, we conclude that AL117190.1, COL4A2‐AS1, LINC00184, MEG3 and MIR22HG act as prognostic biomarkers, whose low expression revealed that patients with breast cancer have better overall survival." (PMID 31613058, 2019). "For example, in a study of 51 human breast cancer cell lines, MIR22HG and MIR155HG are demonstrated to be significantly higher expressed in normal-like cells and basal-like cells respectively." (PMID 27634900, 2016). "Hence, this study aimed to determine the function and molecular mechanism of MIR22HG in breast cancer progression using transcriptomics and biotechnological techniques." (PMID 34446703, 2021). "Since MIR22HG was mainly located in the cytoplasm, we hypothesized that MIR22HG may function as a miRNA sponge in breast cancer cells." (PMID 34446703, 2021). "Notably, results of the rescue experiment suggest that MIR22HG impaired the function of miR-629-5p in breast cancer cells." (PMID 34446703, 2021). "Furthermore, the colony formation assay and Transwell assay results of breast cancer cells co-transfected with miR-629-5p and wild-type/mutant MIR22HG revealed that only the wild-type MIR22HG impaired the function of miR-629-5p in breast cancer cells." (PMID 34446703, 2021). "In addition, to determine the subcellular localization of MIR22HG in breast cancer cells, we separated the nuclear and cytoplasmic RNA of MDA-MB-231 cells." (PMID 34446703, 2021).
breast carcinoma (continued). "Similarly, the MIR22HG expression was lower in the studied breast cancer cell lines, namely MCF7, MDA-MB-231, BT549, and SKBR3, than in the normal breast epithelial cell line MCF10A." (PMID 34446703, 2021). "Therefore, our research reveals the biological function and molecular mechanism of MIR22HG in breast cancer cells and provides novel insights and therapeutic targets for future studies on breast cancer treatment." (PMID 34446703, 2021). "Therefore, our findings reveal the MIR22HG-dependent inhibition of breast cancer cell proliferation and migration via the miR-629-5p/LATS2 pathway, providing new insights and identifying novel therapeutic targets for breast cancer treatment." (PMID 34446703, 2021). "However, the biological function of MIR22HG in breast cancer remains unknown." (PMID 34446703, 2021). "However, the function of MIR22HG in breast cancer remains unknown." (PMID 34446703, 2021). "Notably, MIR22HG stabilized the expression of large tumor suppressor 2 (LATS2), which promoted the LATS2-dependent phosphorylation of YAP1 and suppressed the expression of its downstream target oncogenes, thereby inhibiting the proliferation and migration of breast cancer cells." (PMID 34446703, 2021).
thyroid cancer (5 papers, 2019 to 2022). "Qin and colleagues showed that MIR22HG is downregulated in thyroid cancer including ATC tissues by analyzing TCGA database." (PMID 32760219, 2020). "Bioinformatics analysis indicated that MIR22HG is involved in apoptosis and cell cycle processes, transcription and mRNA splicing regulation as well as and Hippo signaling pathway in thyroid cancer." (PMID 32760219, 2020). "They found that the lower expression levels of MIR22HG is correlated to higher age, lymph node metastasis, and advanced TNM stages as well as higher MIR22HG expression is associated with longer overall and disease-free survival time in thyroid cancer patients." (PMID 32760219, 2020).
esophageal cancer (3 papers, 2019 to 2024). A primary or metastatic malignant neoplasm involving the esophagus. "We found that the c-PARP was increased after knockdown of MIR22HG with siRNA at 72 h, suggested that MIR22HG could regulate both cell proliferation and programs cell death in esophageal cancer cells." (PMID 31291201, 2019).
esophageal adenocarcinoma (2 papers, 2019 to 2020). A malignant tumor with glandular differentiation arising predominantly from Barrett mucosa in the lower third of the esophagus. "However, the role of MIR22HG in esophageal adenocarcinoma (EAC) is poorly understood." (PMID 31291201, 2019).
osteoporosis (2 papers, 2020 to 2023). A condition of reduced bone mass, with decreased cortical thickness and a decrease in the number and size of the trabeculae of cancellous bone (but normal chemical composition), resulting in increased fracture incidence. "In our research, we examined the relative level of MIR22HG in mouse model of osteoporosis and found the expression of MIR22HG was lower compared with SHAM mice." (PMID 32732881, 2020). "In this study, we established osteoporosis mice model and found MIR22HG was significantly downregulated in mouse BMSCs (mBMSCs) from osteoporosis mice compared with the normal mice." (PMID 32732881, 2020). "Overall, these findings suggested that MIR22HG might serve as a promising therapeutic target for osteoporosis treatment and prevention." (PMID 32732881, 2020). "Moreover, we found MIR22HG overexpression promoted osteoclastogenesis of RAW264.7 cells, which indicated that MIR22HG played a significant role in bone metabolism and could be a therapeutic target for osteoporosis and other bone-related diseases." (PMID 32732881, 2020).
acute myeloid leukemia (1 paper, 2025). Acute myeloid leukemia (AML) is a group of neoplasms arising from precursor cells committed to the myeloid cell-line differentiation. "For instance, in acute myeloid leukemia (AML), XBP1s was shown to transcriptionally upregulate miR-22-3p by directly targeting its host gene, MIR22HG, leading to downregulation of SIRT1 and increased chemosensitivity." (PMID 41372991, 2025).
adenoma (1 paper, 2016). A neoplasm arising from the epithelium. "The commonly repressed genes in these two adenoma samples include BCL2L11, TP53INP2, HIST1H1C, TRPM6, MIR22HG, and MIR5047." (PMID 27100181, 2016).
Atrophy (1 paper, 2019). Any weakening or degeneration, especially through lack of use. "We found that 2310065F04Rik (linc-Myh) resulted down-regulated in both atrophy models while Dancr, Gas5, H19, Igf2os, Airn, MiR22hg, Neat1 and Snhg1 were up-regulated in the late phases of atrophy." (PMID 30649422, 2019).
bladder cancer (1 paper, 2020). "We analyzed the TCGA dataset and found the down-regulation of MIR22HG in bladder cancer (BC)." (PMID 32500915, 2020).
colon cancer (1 paper, 2020). "Here, we found that MIR22HG could serve as a ceRNA by sponging miR-25-3p or miR-425-5p in the occurrence and metastasis processes of rectal cancer rather than colon cancer, suggesting its distinct roles in the two cancer types." (PMID 33194594, 2020).
endometrial carcinoma (1 paper, 2020). A malignant tumor arising from the epithelium that lines the cavity of the uterine body. "Evidence has shown that MIR22HG is a target of miR-141-3p in endometrial carcinoma." (PMID 32127004, 2020).
esophageal squamous cell carcinoma (1 paper, 2019). Esophageal squamous cell carcinoma (ESCC) is a type of esophageal carcinoma (EC) that can affect any part of the esophagus, but is usually located in the upper or middle third. "We then analyzed MIR22HG expression from TCGA RNA-seq data including 88 EAC and 95 esophageal squamous cell carcinomas (ESCC)." (PMID 31291201, 2019).
liver cancer (1 paper, 2021). An epithelial or non-epithelial malignant neoplasm that arises from the liver. "Analysis of TCGA database showed that MIR22HG was positively correlated with miR-22-5p expression in liver cancer." (PMID 33718133, 2021). "Inhibition of HDAC2 expression promotes histone acetylation in the MIR22HG promoter region, thereby up-regulating the expression of MIR22HG and promoting the production of miR-22-5p, and ultimately increasing the sensitivity of liver cancer radiotherapy." (PMID 33718133, 2021). "To further confirm whether Santacruzamate A and MIR22HG affect the radiosensitivity of liver cancer in vivo, we established the NC group and radiation 4 Gy only treated group, radiation 4 Gy + Santacruzamate A group, and radiation 4 Gy + Santacruzamate A + MIR22HG knockout group." (PMID 33718133, 2021).
metastatic cancer (1 paper, 2020). A carcinoma which has spread from the original site of growth to another anatomic site. "Interestingly, we found that metastatic cancer patients have even lower levels of MIR22HG as compared with primary cancer." (PMID 32127004, 2020).
metastatic tumors (1 paper, 2023). "It has been proposed that C17orf91, also known as MIR22HG, can be employed as a predictive biomarker for OC patients due to its increased expression between primary and metastatic tumors." (PMID 36902032, 2023).